INS (insulin)
Diseases named in the same sentence as INS in open-access papers (continued):
Sharing a sentence is not in itself a finding about the gene and the disease.
diabetes (continued). "Thetwo groups of patients with diabetes have different experience of the disease.Patients followed at APDP represent mostly type 1 patients, which reflects ahigher number of insulin users." (PMID 35173953, 2020). "While the role of progesterone (P4) in diabetes is controversial, the P4 receptor, progesterone receptor membrane component 1 (PGRMC1), is known to stimulate pancreatic insulin secretion." (PMID 33005004, 2020). "Percentage total weight loss was correlated to improvement in insulin levels in patients of all subgroups, without diabetes (Spearman rank correlation coefficient, r = − 0.213, p < 0.001), prediabetics (r = − 0.424, p < 0.001), as well as diabetics (r = − 0.505, p < 0.001)." (PMID 32314253, 2020). "For example, Tandem Diabetes Care has gained approval in the US and Canada for their t:slim X2TM insulin pump with Basal-IQTM technology." (PMID 32625083, 2020). "In models of metabolic syndrome, diabetes, and in overweight subjects, the GW501516 agonist of PPARβ/δ lowers plasma glucose and/or insulin levels." (PMID 33198317, 2020). "Both the STZ and FRB groups showed a higher level of blood glucose and a lower level of plasma insulin compared to the control group, indicating the efficiency of STZ in inducing diabetes during the one month of treatment." (PMID 32806520, 2020). "Muniyappa and colleagues have astutely proposed that this might mediate the association between diabetes and COVID-19 severity, but hypothesized that elevated glucose rather than elevated insulin levels were the underlying metabolic driver of increased ACE2 expression." (PMID 32574288, 2020). "The other, the Diabetes Prediction and Prevention (DIPP) Study performed to investigate the potential effect of nasal insulin on reducing the incidence of T1D." (PMID 32872668, 2020). "Notably, the metabolite pattern in OB and T2D groups differed between urine and plasma, suggesting that urinary BCAAs and their intermediates behaved as a more specific biomarker for T2D, while plasma BCAAs associated with the obese, insulin resistant state independent of diabetes status." (PMID 32589682, 2020). "We showed that SC-β cells, including insulin-positive cells, can be infected with CVB4 to study the etiology of virus-induced diabetes." (PMID 32093375, 2020). "Diabetes mellitus, especially T2DM, is a metabolic disease characterized by abnormally hyperglycemia due to impaired insulin secretion and/or insulin action." (PMID 33002109, 2020). "Type II DM, formerly classified as non-insulin-dependent diabetes, is caused by ineffective pancreatic insulin secretion and/or insulin usage by the body." (PMID 32118053, 2020). "As one of the main factors in the pathogenesis of type 2 diabetes mellitus (T2DM), insulin resistance (IR) is characterized by the decline of insulin sensitivity in insulin target organs." (PMID 31908653, 2020). "In the replication HKDB cohort including 3,939 patients (mean age 60.9 ± 10.9 years; 59.5% men; median duration of diabetes 7 [IQR: 3–13] years), 172 (4.4%) progressed to insulin use during a median follow-up period of 1.9 (IQR: 1.5–2.3) years." (PMID 32722720, 2020). "Zinc supplementation in a trial of pre-diabetic individuals reduced progression to diabetes along with improvements in fasting glucose, oral glucose tolerance test (OGTT) results, insulin resistance, and blood lipids." (PMID 32341338, 2020). "Exercise enhances insulin-induced phosphorylation of TBC1D4 and improves insulin sensitivity in diabetes." (PMID 32178449, 2020). "We have previously shown that diabetes-induced increases in TNFα can increase IRS-1Ser307 phosphorylation in retinal cell types, which results in dysfunctional insulin signal transduction." (PMID 32432228, 2020). "Unfortunately, in the treatment of type 2 diabetes mellitus complicated with community-acquired pneumonia (T2DM-CAP), modern medicine is still faced with enormous challenges because of insulin resistance and drug-resistant bacteria." (PMID 32925778, 2020).
diabetes (continued). "Insulin resistance in AD and diabetes can lead to hyperinsulinemia, thereby, saturating insulin-degrading enzymes (IDE) for insulin and Aβ degradation." (PMID 32365816, 2020). "Intriguingly, IRS-2-deficient mice are more susceptible to diabetes than IRS-1 knockout mice because of the impairment of insulin secretion, indicating that IRS-2 contributes to the molecular basis for diabetes." (PMID 32610588, 2020). "According to these results, the most important pathways related to treating of diabetes by SQC are PI3K-Akt, HIF-1, TNF, insulin resistance, FoxO, MAPK, AMPK, and insulin signal pathways." (PMID 32595730, 2020). "Quite contrary to the comparison of admission diabetes therapy between LHLH and SMH, insulin treatment dominated the discharge pharmacotherapy at SMH while OADs-only treatment and insulin contributed equally at LHLH." (PMID 32267843, 2020). "Reduced osteocalcin levels, which have been previously associated with insulin resistance and increased risk for diabetes, may in fact contribute to changes in VAT levels, as mice lacking osteocalcin exhibit higher VAT levels as well as glucose intolerance and impaired insulin secretion." (PMID 32512872, 2020). "On the contrary, in insulin-resistant animals, GLUT1 in the S3 segment decreased in the first 3 months of diabetes and increased in the next 3 months, when cortical GLUT2 activity enhanced." (PMID 32377524, 2020). "Insulin was the first genetically engineered peptide hormone and was approved by the FDA in 1982 for the treatment of diabetes." (PMID 31941022, 2020). "Diabetes Mellitus is a chronic disease estimated to affect nearly 415 million adults worldwide, characterized by an abnormal increase of blood Glucose (hyperglycemia) caused by lack of insulin production (type 1 diabetes, T1DM) or by predominant insulinoresistance (type 2 diabetes, T2DM)." (PMID 33120406, 2020). "In addition to the antioxidant properties of phlorotannins, promising anti-diabetes effects have also been demonstrated for these compounds via the inhibition of key enzymes, prevention of the formation of advanced glycation end products, improving insulin sensitivity and others." (PMID 33203128, 2020). "The results suggest that this co-supplementation can improve fasting serum glucose, insulin and HDL-C and beta cell function in reproductive-aged women with pre-diabetes and hypovitaminosis D." (PMID 32435279, 2020). "Of the 38 (13.1%) patients with diabetes treated with DPP4 inhibitors, 32 (11.07%) were on other oral agents and/or insulin." (PMID 32385343, 2020). "Type 2 diabetes mellitus (T2DM) is a chronic and progressive metabolic disease characterized by hyperglycemia due to the defects of insulin secretion and/or action." (PMID 32334592, 2020). "BXXD protected MIN6 cells against t-BHP-induced apoptosis and improved insulin secretory function through modulation of the PI3K/AKT pathway and the downstream FOXO1, thus suggesting a novel therapeutic approach for type 2 diabetes mellitus (T2DM)." (PMID 32377518, 2020). "Even though the exact link between diabetes mellitus and cognitive impairment is not fully elucidated, some authors have revealed that hyperglycemia, vascular disease, hypoglycemia, insulin resistance, and amyloid deposition can be associated with cognitive dysfunction, especially in elderly people." (PMID 33071792, 2020). "Factors significantly associated with BI discontinuation were hospital level, patient recruitment setting, age, education level, out‐of‐pocket ratio, BMI, diabetes duration, SMBG, BI types and insulin regimen." (PMID 32318640, 2020). "Diabetes mellitus (DM) is a metabolic disorder related to reduced sensitivity of tissue receptors toward insulin, abnormal insulin signaling, and deteriorating function of β-cells, which lead to abnormal glucose level, sub-clinical inflammation, and increased oxidative stress." (PMID 33255206, 2020).
diabetes (continued). "SGLT2 inhibitors, a new group of drugs that block glucose resorption through an insulin-independent mechanism, i.e., in kidney by blocking SGLT2 transport, are a promising new therapy for diabetes." (PMID 33105667, 2020). "Indeed, CBV1 was also observed to increase the risk of T1D in the prospective Diabetes Prediction and Prevention (DIPP) study, potentially cause damage to β-cells and might lead to the induction of an autoimmune response against insulin during T1D pathogenesis." (PMID 33071971, 2020). "Type-2 diabetes mellitus (T2DM) is a complex disease characterized by reduced pancreatic islets β-cell mass and impaired insulin release from these cells." (PMID 33195407, 2020). "Type 2 diabetes mellitus (T2DM) can be due to insufficient insulin production by the pancreatic beta cells, or due to insulin resistance in the body." (PMID 32170854, 2020). "In addition to having a significant effect on different signaling and metabolic pathways that can improve diabetes, it enhances mitochondrial biogenesis and reduces mitochondrial damage, oxidative damage, inflammation, lipid accumulation, liver steatosis and improves the action of insulin." (PMID 33375293, 2020). "Some previously published studies have suggested that moderate consumption of 30 g/d of alcohol (2 drinks per day) is beneficial to insulin sensitivity and triglyceride concentration in nondiabetic postmenopausal women and could decrease the risk of diabetes and improve insulin resistance." (PMID 32639947, 2020). "Type 2 diabetes mellitus (T2DM) typically affects many metabolic pathways, resulting in β-cell dysfunction, insulin resistance, abnormal blood glucose levels, inflammatory processes, excessive oxidative reactions, and impaired lipid metabolism." (PMID 33287318, 2020). "This suggests that the ability to improve insulin sensitivity in response to exercise is preserved in T2DM patients, despite an impaired beta-cell function and longer diabetes duration, well in line with the indications of this review." (PMID 32903679, 2020). "Type 2 diabetes mellitus (T2DM) is the most prevalent metabolic disorder characterized by chronic hyperglycemia and an inadequate response to circulatory insulin by peripheral tissues resulting in insulin resistance." (PMID 32215179, 2020). "Diabetes mellitus (DM) refers to abnormalities in the metabolic processing of carbohydrates, fats and proteins that is characterized by persistent hyperglycemia as a result of insufficient insulin secretion, impaired insulin action or both." (PMID 33537003, 2020). "Diabetes mellitus type 2 (DM2), characterized by resistance to insulin, is responsible for approximately 90% of diabetes cases." (PMID 32120955, 2020). "In accordance with animal models, humans with severe IR or diabetes have elevated intestinal MTP expression and protein abundance compared to more insulin sensitive individuals." (PMID 32231641, 2020). "Besides, γT3 suppressed the progression of diabetes in BKS.Cg-Dock7m+/+ Leprdb/J diabetic mice with an increase of adiponectin level, reduced the loss of pancreatic β-cells and increased the average islet size, size distribution, and insulin-positive area with lesser immune cell infiltration." (PMID 31963885, 2020). "Consequently, suboptimal insulin values as well as low insulin receptor sensitivity could eventually contribute to a reduction in acetylcholine, which leads to a likely biochemical link between diabetes and AD." (PMID 32503113, 2020). "Hyperglycemia and chronic hyperinsulinemia in type 2 diabetes mellitus (T2DM), or related to exogenous insulin overdose in T1DM, play an essential role in haemostasis alteration found in DM." (PMID 33031385, 2020). "Diosgenin was shown to promote insulin secretion and influence beta cell regeneration in STZ-induced diabetes in rats through PPARγ activation in adipose tissue and oxidative stress modulation." (PMID 32408715, 2020).
diabetes (continued). "Alterations in insulin and insulin-like growth factor type 1 (IGF-1) signalling pathways have been identified as the main drivers that lead to the development of both diabetes and cancer." (PMID 32708201, 2020). "In addition, recombinant OCN injection improved glucose tolerance, insulin expression in β-cells, increased β-cell proliferation and insulin secretion, augmented adiponectin expression, decreased fat mass, and prevented high fat diet-induced obesity and diabetes in WT mice." (PMID 33537005, 2020). "A negative correlation of IGFBP2 with body composition, BMI, metabolic syndrome, type 2 diabetes mellitus, or NAFLD, and a positive correlation to insulin sensitivity independent to BMI were described." (PMID 32532003, 2020). "As the most common type of diabetes, type 2 diabetes mellitus (T2DM) begins with insulin resistance induced by hyperglycemia, and accordingly body cells fail to respond and uptake of insulin in the body." (PMID 32017705, 2020). "Type 2 diabetes mellitus (T2DM) is characterized by insulin resistance and a relative defect in insulin secretion." (PMID 33123595, 2020). "Diabetes mellitus (DM) results from malfunctions in insulin secretion and/or insulin function." (PMID 32210144, 2020). "Our results showed that after induction of diabetes, FBS, and HbA1C increased, and serum insulin decreased significantly, but glycosylated albumin and serum BDNF did not change significantly." (PMID 32405353, 2020). "STX4 overexpression restricted to pancreatic beta-cells increases the capacity for insulin secretion, promotes glucose tolerance and protects STZ-treated mice from developing diabetes." (PMID 32226409, 2020). "Type 1 diabetes mellitus (T1DM) is a chronic disease, in which the autoimmune system destroys the pancreatic beta cells responsible for insulin production." (PMID 33374507, 2020). "In our patient, diabetes was diagnosed 2 years prior to the diagnosis of SPS, and SPS was diagnosed shortly after the initiation of insulin therapy." (PMID 32982980, 2020). "Diabetes mellitus (DM) refers to a group of metabolic diseases characterized by aberrant glucose metabolism and persistent hyperglycemia resulting from defects in insulin secretion, insulin action, or both." (PMID 32742869, 2020). "In univariable regression analysis, a negative correlation between serum total magnesium concentrations and age, diabetes duration, BMI, HbA1c, use of metformin, sulfonylurea derivatives, DPP4 inhibitors, insulin and RAAS blocking medication was demonstrated." (PMID 31650393, 2020). "We monitored the blood glucose level, serum insulin, miR222 expression and TIMP‐3 expression, respectively, after the induction of diabetes from day 4 to day 42 during the bone healing." (PMID 31691506, 2020). "Type 2 diabetes mellitus (T2DM) is a complex, heterogeneous and chronic metabolic disorder, and is characterized by defects in insulin secretion and/or insulin action leading to hyperglycemia." (PMID 32329795, 2020). "For example, in the Diabetes Control and Complications Trial (DCCT), patients with type 1 diabetes were randomized to intensive or standard insulin regimens to control their blood sugars." (PMID 31914992, 2020). "Infusion of BCAA in humans acutely worsen insulin sensitivity and elevations in plasma BCAA levels can be detected in people more than 10 years before developing diabetes." (PMID 32386512, 2020). "Studies have proposed that impaired insulin signaling and consequent insulin resistance in both metabolic and neuronal tissues are common factors in type 2 diabetes and diabetic PN, which suggests that efforts to reduce the impact of diabetes may be effective in reducing DPN symptoms." (PMID 32080785, 2020). "Type 2 diabetes mellitus (T2DM) is characterized by insulin resistance and the dysfunction of insulin producing β-cells in the islets of Langerhans of the pancreas." (PMID 32375753, 2020).
diabetes (continued). "Elevated levels of fasting insulin release and insufficient glucose-stimulated insulin secretion (GSIS) are hallmarks of diabetes." (PMID 32934005, 2020). "Related to the physiological symptoms of diabetes, other studies focusing on the relationship between SAD and insulin action have shown that SAD measurements had strong correlations with metabolic factors including insulin sensitivity and insulin resistance." (PMID 32677929, 2020). "Recent technological advances in diabetes treatment have integrated continuous subcutaneous insulin delivery (CSII) with CGM, where insulin delivery can be automated by sensor glucose (SG)-driven algorithms." (PMID 31953687, 2020). "Very few participants were on insulin or a combination of insulin and oral medication but this was also typical of the population tested and not because of the researchers missing participants on insulin who may have poorer outcomes and perhaps a more challenging diabetes care." (PMID 32685189, 2020). "Adult-onset autoimmune diabetes (AID) has two different phenotypes: classic type 1 diabetes mellitus (T1DM), with insulin requirement just after diagnosis, and latent autoimmune diabetes in adults (LADA)." (PMID 33292447, 2020). "Type 1 diabetes mellitus (T1DM) is a chronic, immune-mediated disease characterized by the destruction of insulin producing cells and persistent hyperglycemia." (PMID 32846751, 2020). "It is most likely that the main mechanisms of anti-diabetes involve suppressing TLR2 signalling pathway, stimulating the insulin signalling pathway and the interactions of the two through TNF-α based upon the bioactive compounds identified from WEM." (PMID 31752797, 2019). "As a PPAR-γ agonist and insulin-sensitizing drug, PIO is involved in the metabolism of glucose and exerts cardiovascular protective effect in diabetes mellitus." (PMID 31829402, 2019). "IPA significantly decreased the insulin and C-peptide levels in the plasma of HFD mice, suggesting the protective action of IPA against pancreatic dysfunction in HFD-induced diabetes." (PMID 31731426, 2019). "In diabetic AKI patients, a low insulin activity can reduce the albumin synthesis speed, which can improve with insulin administration." (PMID 30646533, 2019). "The same group of authors conducted desensitization experiments in the diabetes-prone NOD mice, which are considered a model of autoimmune diabetes, by treating them with dexamethasone and the insulin-derived, MHC II-restricted peptide antigen B:9–23." (PMID 30845709, 2019). "The most accepted porcine model of diabetes is STZ-induced type 1 diabetes, where glucose and insulin secretion remain at a very similar level to human diabetic patients." (PMID 30987291, 2019). "It has been found that insulin secretion in INS1 cells is reliant on Fis1 level and dysregulation of interface between nutrient input and insulin secretion is highly impacted in type 2 diabetes mellitus." (PMID 31053718, 2019). "Diabetes mellitus (DM) is a chronic condition that occurs when there are raised blood glucose levels, arises from pancreas’ failure to secret enough insulin and/or decreased response to insulin." (PMID 30823598, 2019). "At baseline, 4,192 patients (49.1%) received oral medical treatment alone for diabetes, 453 received insulin alone (5.3%), 14 received a GLP-1 analogue alone (0.2%), and 1,973 received a combination of oral treatment and insulin (23.1%)." (PMID 31747392, 2019). "Most of them suffered from type 2 diabetes mellitus (T2DM), which is characterized by insulin resistance, hyperglycemia, and inadequate insulin secretion which results from progressive pancreatic β-cell function decline." (PMID 31950036, 2019). "Autoimmune diabetes, also known as Type 1 diabetes mellitus (T1DM), is an autoimmune-mediated disease characterized by selective destruction of insulin-producing pancreatic β-cell." (PMID 31889967, 2019).